ADCY5 (adenylate cyclase 5)
Diseases named in the same sentence as ADCY5 in open-access papers (continued):
Sharing a sentence is not in itself a finding about the gene and the disease.
Obesity (21 papers, 2010 to 2025). Accumulation of substantial excess body fat. "In the current study, we analyzed relationships between ADCY5 mRNA expression in human visceral and subcutaneous adipose tissue, metabolic traits related to obesity and the ADCY5 genotype at the risk SNP rs11708076." (PMID 25793868, 2015). "Indeed, missense mutations have been previously reported for this gene in the context of obesity while another member of this gene family, ADCY5, has also been extensively implicated in metabolic traits." (PMID 39813287, 2025). "In addition, ADCY5 genetic variants have been associated with lower birth weight, gestational diabetes, and parameters of insulin sensitivity in children with obesity." (PMID 33919448, 2021). "For the common influencing factors of AD and DM, such as obesity and depression, the expression of ADCY5 is increased." (PMID 36923118, 2023). "Adcy5–/– mice are protected against high-fat diet-induced obesity, insulin resistance, heart failure, myocardial apoptosis and have reduced whole-body oxidative stress." (PMID 33919448, 2021). "Our finding in a cohort with a mean age of 11.5 years and hence shorter exposure to obesity and other adverse (life style) factors, supports a role of ADCY5 in the pathophysiology of insulin resistance, independent of obesity." (PMID 21789219, 2011). "ADCY5 gene expression in adipose tissue is related to obesity in men and mice." (PMID 36923118, 2023). "In conclusion, our data did not support beneficial effects on obesity and insulin sensitivity described for other Adcy5-deficient mouse models." (PMID 33919448, 2021). "In male mice, a 20-week HFD challenge started at 6 weeks of age caused obesity without significant differences between the body weight curves of Adcy5–/– and Ctrl mice." (PMID 33919448, 2021). "Our study was inspired by previous reports that mice with a disruption of Adcy5 are protected against the development of high fat feeding-induced obesity, glucose intolerance, insulin resistance, heart failure, have reduced oxidative stress and increased longevity." (PMID 33919448, 2021). "Five variants were top weighted (above the threshold of 0.75) in more than one cluster: CDC123/CAMKID (Beta Cell and Proinsulin), HSD17B12 (Beta Cell and Obesity), ADCY5 (Beta Cell and Lipodystrophy), CCND2 (Proinsulin and Lipodystrophy), and HNF4A (Beta Cell and Proinsulin)." (PMID 30240442, 2018). "We therefore tested the hypothesis that ADCY5 mRNA expression in human and mouse AT is related to obesity, fat distribution, T2D in humans and high fat diet (HFD) in mice." (PMID 25793868, 2015). "However, independently of the ADCY5 genotype, AT ADCY5 expression is related to obesity and may contribute to adverse fat distribution and adipose tissue dysfunction." (PMID 25793868, 2015). "Therefore, the initiation and progression of obesity may be inhibited by blocking ADCY5 activity." (PMID 39126035, 2024). "Univariate correlations between ADCY5 mRNA expression in visceral (VAT) and subcutaneous (SC) adipose tissue and parameters of obesity, insulin sensitivity, and inflammation." (PMID 25793868, 2015). "In humans and mice, visceral ADCY5 expression is significantly higher in obese compared to lean individuals, and changes in adipose tissue ADCY5 expression are related to obesity and fat distribution, but not to impaired glucose metabolism and T2DM." (PMID 36923118, 2023). "In our model, ablation of Adcy5 at the whole-body level did not protect mice against obesity under high-fat diet conditions." (PMID 33919448, 2021). "In humans, we showed that AT ADCY5 expression is related to obesity and fat distribution, but not with impaired glucose metabolism and T2D." (PMID 33919448, 2021). "Here, we showed that females lacking Adcy5 developed severe obesity under HFD, comparable to male mice." (PMID 33919448, 2021).
Obesity (continued). "Mice with a whole-body deletion of Adcy5 (Adcy5–/–) do not develop obesity, glucose intolerance and insulin resistance, have improved cardiac function and increased longevity." (PMID 33919448, 2021). "Unexpectedly, we found that Adcy5–/– mice of both sexes were not protected against obesity and impaired glucose metabolism." (PMID 33919448, 2021). "Our results suggest that changes in AT ADCY5 expression are related to obesity and fat distribution, but not with impaired glucose metabolism and T2D." (PMID 25793868, 2015). "Additionally, our Adcy5–/– model was characterized by a significantly lower voluntary exercise activity in both sexes and diets, suggesting that lower activity may underlie the unexpected phenotype without protection against obesity and its associated cardio-metabolic abnormalities." (PMID 33919448, 2021). "Taken together, Adcy5–/– mice were not protected against HFD-induced obesity." (PMID 33919448, 2021).
Dyskinesia (19 papers, 2016 to 2025). A movement disorder which consists of effects including diminished voluntary movements and the presence of involuntary movements. "In conclusion, ADCY5 variants are characterized by nocturnal dyskinesia, which improves with caffeine, while GNAO1-related disorders usually present with dystonic storms." (PMID 40724495, 2025). "In recent years, increased interest has emerged in the potential therapeutic role of caffeine in certain types of dyskinesia, particularly those associated with mutations in the ADCY5 gene." (PMID 40869757, 2025). "The most pronounced effects on cAMP reduction were observed in ADCY5 R418W mutant cells, a mutation found in the majority of individuals with ADCY5‐related dyskinesia." (PMID 40079709, 2025). "Preliminary clinical studies have shown promising results regarding the use of caffeine for treating ADCY5-associated dyskinesia." (PMID 40869757, 2025). "Mutations in ADCY5 can lead to abnormal regulation of cAMP levels, which is believed to contribute to the development of dyskinesia." (PMID 40869757, 2025). "As ADCY5-related dyskinesia is caused by gain-of-function ADCY5 amino acid-exchange mutations, reduction of cAMP levels will result in an improvement in movement disorders." (PMID 36867608, 2023). "The constellation of neurological disorders associated with ADCY5 mutations includes conditions of variable severity, ranging from severe early-onset neurodevelopmental disorder with dyskinesia to familial dyskinesia with facial myokymia (FDFM)." (PMID 36003298, 2022). "Adcy5 is of particular interest since it is the causative gene of a dyskinesia due to the dominant gain of function mutations." (PMID 34207710, 2021). "Of note, ADCY5‐related dyskinesia appears to result from either a gain or loss‐of‐function mechanism, although the underlying mechanisms accounting for these differences are not yet fully understood." (PMID 34631954, 2021). "We suggest testing for ADCY5 mutations patients previously diagnosed with dyskinetic cerebral palsy when exacerbations of dyskinesia are clearly sleep-related." (PMID 28511835, 2017). "Among these, ADCY5 pathogenic variants have been related to dyskinesia with orofacial involvement, both in autosomal dominant and recessive forms (OMIM#606703 and #619647, respectively), and to a neurodevelopmental disorder with hyperkinetic movements and dyskinesia (OMIM#619651)." (PMID 40724495, 2025). "Mutations in the ADCY5 gene cause increased enzymatic activity, leading to an overproduction of cAMP and clinically resulting in abnormal involuntary movements referred to as dyskinesia." (PMID 40079709, 2025). "Additionally, episodes of dyskinesias in patients with ADCY5 mutations are noteworthy, consisting of severe, sleep-disrupting movements occurring during stages N2 and N3 of sleep." (PMID 38903163, 2024). "All ADCY5 mutations result in kinetic disorders or dyskinesia that effect all muscles." (PMID 36867608, 2023). "However, it was notable that all 4 kindreds presenting with the more severe phenotype, in terms of dyskinesias, axial hypotonia, and motor developmental delay, had the ADCY5 p.R418W mutation." (PMID 27061943, 2016). "ADCY5‐associated dyskinesia may be under‐recognized, and its diagnosis has important prognostic, genetic, and therapeutic implications." (PMID 27061943, 2016). "As mutations in the Atp1a3 gene are known to be related to dyskinesia, epilepsies and Parkinson’s disease this could be a relevant finding in the context of other reports describing a connection between the loss of Adcy5 and movement disorders like dyskinesia or autism-like behavior." (PMID 33919448, 2021). "ADCY5‐related dyskinesia manifests through a variety of impaired voluntary movements, including, but not limited to, choreoathetosis, dystonia, myoclonus, and/or axial hypotonia, ultimately resulting in poor motor control." (PMID 40079709, 2025).
Dyskinesia (continued). "ADCY5, known to produce cAMP, which regulates neuronal function, was reported to be related to dyskinesia or Parkinsonian-like motor dysfunction in an ADCY5-null mouse model." (PMID 39085355, 2024). "Since the first description, the phenotype associated to ADCY5 mutations has largely broadened and consequently, the original term FDFM has been replaced by a more comprehensive definition (ADCY5-related dyskinesias)." (PMID 29086067, 2017). "The high expression of ADCY5 in the striatum has led to the hypothesis that altered dopamine signaling in response to stress is responsible for ADCY5-related dyskinesia." (PMID 34177764, 2021). "Further research will be needed in order to identify the molecular and neurophysiological mechanisms influencing the phenotypic variability of ADCY5-related dyskinesia and to determine whether an effective pharmacological agent can be found to treat this condition." (PMID 28229249, 2017). "Individuals with ADCY5‐related dyskinesia identified to date have overlapping but not identical clinical manifestations with wide‐ranging clinical severity." (PMID 34631954, 2021). "The natural history of ADCY5-related dyskinesias is still poorly defined and no or little progression of movement disorder has been observed in previous reports." (PMID 28511835, 2017).
heart failure (12 papers, 2013 to 2024). Inability of the heart to pump blood at an adequate rate to meet tissue metabolic requirements. "Interestingly, upon genetic ablation of Adcy5, it was shown that AC5 is protective against cardiac dysfunction in pressure overload induced cardiac hypertrophy, thus suggesting that the stimulation of AC5 could potentially be a protective therapeutic approach in heart failure." (PMID 29751502, 2018).
Chorea (11 papers, 2015 to 2024). Chorea (Greek for 'dance') refers to widespread arrhythmic involuntary movements of a forcible, jerky and restless fashion. "Given that pathogenic mutations in both PDE10A and ADCY5 cause chorea (even though PDE10A and AC5 exert opposite effects on cAMP levels), one would expect that the p.Phe300Leu and p.Phe334Leu variants exert a deleterious effect on PDE enzyme activity." (PMID 27058447, 2016). "ADCY5 is associated with various neurological syndromes in non-cancer tissues and can cause chorea, a type of neurological syndrome." (PMID 31803734, 2019). "Further genetic investigation, including SETX and other chorea-related genes (i.e., ADCY5, PRNP, and VPS13A) are needed, but are lacking due to limitations of laboratory conditions." (PMID 36596053, 2022). "Indeed, ADCY5- and PDE10A-related disorders seem to show a static or mildly progressive course, while GNAO1-related movement disorders are characterized by progressive chorea which can become life-threatening in some patients." (PMID 29948482, 2018).
Anxiety (7 papers, 2010 to 2022). Intense feelings of nervousness, tension, or panic often arise in response to interpersonal stresses. "Several anxiety-associated genes had direct interactions with striatal development genes, such as PRKCA with ADCY5 and DLX3, and ESR1 with ISL1." (PMID 34526518, 2021). "We first searched for significant correlations between anxiety-like behavior and gene expression in all mice combined and found that Trkb, Htr2c, Adcy5, and App were negatively correlated with anxiety-like behavior." (PMID 24199867, 2013). "Adenylate cyclase 5 (AC5) is highly expressed in the striatum as is AKAP5 and AC5 KO mice show reductions in several anxiety like behaviors." (PMID 20428246, 2010). "Similarly, ADCY5-null mice exhibit poor stress-coping responses, indicating a critical role of ADCY5 in the regulation of anxiety and stress." (PMID 35307032, 2022). "A previous study reported that Adcy5 knockout mice have poor stress coping responses, a finding that is consistent with our current finding that chronically stressed XY- mice have lower Adcy5 gene expression and increased anxiety-like behavior compared to XX mice." (PMID 24199867, 2013). "Interestingly, we also found a negative correlation of Adcy5 with anxiety-like behavior." (PMID 24199867, 2013).
cardiomyopathy (7 papers, 2012 to 2024). A disease of the heart muscle or myocardium proper. "In contrast to this, ADCY5 overexpression but not disruption in mice results in a cardiomyopathy." (PMID 34631954, 2021).
autism (5 papers, 2019 to 2025). Persistent deficits in social interaction and communication and interaction as well as a markedly restricted repertoire of activity and interest as well as repetitive patterns of behavior. "Loss of Adcy5 in mouse dorsal striatum lead to autism-like behaviour." (PMID 34573345, 2021). "Noteworthy, independent groups reported that mice with a genetic disruption of Adcy5 exhibited increased repetitive behaviors and sociability deficits similar to autism-like behavior." (PMID 33919448, 2021). "We tested whether LpEV treatment could improve autism-like behaviors in Adcy5-KO mice." (PMID 40164687, 2025).
breast cancer (4 papers, 2014 to 2024). A primary or metastatic malignant neoplasm involving the breast. "In addition, previous studies indicate that the expression of ADCY5 is reduced and contributes to the progression of breast cancer." (PMID 39104385, 2024).
Hyperglycemia (4 papers, 2015 to 2022). An increased concentration of glucose in the blood. "Carriers of the high risk single nucleotide polymorphism (SNP) rs11708067 within the ADCY5 gene have lower ADCY5 mRNA expression in islets associated with fasting hyperglycemia and higher T2D risk." (PMID 33919448, 2021). "Recently, it has been shown that ADCY5 mRNA expression in islets is lower in carriers of high risk alleles at rs11708067 and maybe linked to fasting hyperglycemia and higher T2D risk." (PMID 25793868, 2015). "We measured ADCY5 mRNA expression in paired samples of visceral and subcutaneous adipose tissue from 244 individuals with a wide range of body weight and parameters of hyperglycemia, which have been genotyped for rs11708067." (PMID 25793868, 2015).
melanoma (4 papers, 2014 to 2025). A malignant, usually aggressive tumor composed of atypical, neoplastic melanocytes. "Overall, our findings reveal novel roles of Adcy3a and Adcy5 in regulating pigmentation in vertebrates and provide an optimal animal model for studying the roles of cAMP signaling in melanocyte development and potential skin malignancies such as melanoma." (PMID 36430661, 2022). "Although in vitro studies have shown that knockdown of Adcy5, Adcy6, and Adcy9 isoforms, respectively, appears to reduce a-MSH-stimulated melanogenesis in mouse B16F10 melanoma cells, none of the individual Adcy isoform knockout mice show defects in the pigmentation of skin and hair." (PMID 36430661, 2022).
benign hereditary chorea (3 papers, 2016 to 2022). "Mutations in a second gene, ADCY5, coding for the adenylate cyclase 5, have been found to be another cause of benign hereditary chorea." (PMID 35079915, 2022).
colon cancer (3 papers, 2022 to 2024). "In T2DM patients, elevated methylation levels of ADCY5 are associated with an increased risk of developing colon cancer, and in glioblastoma, ADCY5 functions as a tumor suppressor, implies that similar mechanisms could be at play in colorectal cancer." (PMID 39678375, 2024). "ADCY5 (adenylate cyclase 5) is a member of the membrane-bound adenylate cyclase family, which converts adenosine triphosphate into the second messenger cyclic adenosine monophosphate and pyrophosphate and is regarded as a candidate diagnostic biomarker for colon cancer." (PMID 37670265, 2023). "Thus, our model identifies important markers such as SLC2A1 and ADCY5 which can provide valuable prognostic information for colon cancer patients, potentially guiding treatment decisions." (PMID 39678375, 2024). "Despite these limitations, our model successfully identified prognostic markers for colon cancer, particularly genes such as SLC2A1 and ADCY5, which are also supported by existing literature." (PMID 39678375, 2024). "Collectively, our results were consistent across several datasets, suggesting that ADCY5 and SLC2A1 could potentially serve as robust prognostic biomarkers for CC, and underscore a significant role played by the microenvironment in the progression of colon cancer." (PMID 39678375, 2024).
dilated cardiomyopathy (3 papers, 2012 to 2025). Cardiomyopathy which is characterized by dilation and contractile dysfunction of the left and right ventricles. "Among these reported genes, two genes (ADCY5 and TCF7L2) were also found annotated to ARVC and dilated cardiomyopathy pathways." (PMID 22973544, 2012).
glioblastoma (3 papers, 2024 to 2025). The most malignant astrocytic tumor (WHO grade IV). "Its expression is frequently downregulated in glioblastoma and other cancers, and higher ADCY5 levels are associated with better prognosis." (PMID 41331166, 2025). "Adenylyl cyclase (AC) isoforms played a key role in the multiple cancer pathology, However, the expression, prognostic value and function of ADCY5 in Glioblastoma (GBM) have not been reported yet." (PMID 39319137, 2024).
Parkinson disease (3 papers, 2018 to 2022). A progressive degenerative disorder of the central nervous system characterized by loss of dopamine producing neurons in the substantia nigra and the presence of Lewy bodies in the substantia nigra and locus coeruleus. "Interestingly, we found pathways relevant to the pathogenesis of Parkinson’s, Alzheimer ́s, Huntington ́s or non-alcoholic fatty liver disease to be upregulated in female Adcy5–/– mice." (PMID 33919448, 2021).
alcoholism (2 papers, 2021 to 2022). "The authors found a significant association of the MDD–alcoholism phenotype with haplotypes (i.e., SNPs) within ADCY5 (type 5 adenylyl cyclase protein gene) on chr." (PMID 34201295, 2021). "Interestingly, the GO term “alcoholism” was enriched in genes associated with the “CGI-free intergenic UMR” category, including Shc3, Shc4, Araf, Fosb, Hdac11, Adcy5, Creb3l2, Gnai2, Grin2d, and Ppp1r1b." (PMID 35205351, 2022).
cervical dystonia (2 papers, 2022 to 2025). "Caffeine was mainly used in patients with a mutation in the ADCY5 gene; not all patients showed remission of symptoms, especially patients with static ADCY5-related cervical dystonia." (PMID 40943684, 2025).
depression (2 papers, 2021 to 2023). "They found decreased REST mRNA expression and increased mRNA expression of CRH, adenylate cyclase 5 and the tumor necrosis factor superfamily in patients with major depressive disorder during an acute episode but not in remission." (PMID 33804468, 2021).
epilepsies (2 papers, 2021 to 2022). "GNAL and ADCY5 genes have not been associated with epilepsy so far." (PMID 36003298, 2022). "While the clinical phenotype associated with ADCY5 and GNAL is characterized by movement disorder in the absence of epilepsy, GNAO1, GNB1, PDE2A, PDE10A, and HPCA have a broader clinical phenotype, encompassing movement disorder, epilepsy, and neurodevelopmental disorders." (PMID 36003298, 2022).